GADD45G (growth arrest and DNA damage inducible gamma)
Diseases named in the same sentence as GADD45G in open-access papers (continued):
Sharing a sentence is not in itself a finding about the gene and the disease.
sarcoma (1 paper, 2021). A usually aggressive malignant neoplasm of the soft tissue or bone. "Blocking the activity of the PI3K-Akt signalling pathway in sarcoma cells leads to an increase in GADD45G gene expression, halts the cell cycle and facilitates apoptosis." (PMID 34360791, 2021). "We have shown that established Rh30 and RD sarcoma cell lines cultured in the presence of the tested PRMT inhibitors have decreased expression of TNC, NRP1, MYOF, EMP1, OLFML3 and CCND1 and increased expression of the GADD45G gene." (PMID 34360791, 2021).
Sepsis (1 paper, 2019). Sepsis is defined as life-threatening organ dysfunction caused by a dysregulated host response to infection. "To date, no data exists which implicates GADD45γ in apoptotic tubular cell death in AKI inflicted by direct renal insults such as renal ischemia, sepsis and nephrotoxins." (PMID 30794682, 2019).
status epilepticus (1 paper, 2017). Status epilepticus is defined as a continuous seizure lasting more than 30 min, or two or more seizures without full recovery of consciousness between any of them. "For example, Gadd45g plays a role in neuronal apoptosis during KA-dependent status epilepticus." (PMID 26993296, 2017).
steatosis (1 paper, 2020). Increased lipid within the cytoplasm of cells. "Of the top-ranked 10 genes, two genes (CYP7A1 and PEG10) were significantly up-regulated in both steatosis and NASH patients, while eight genes (FOSB, FOS, IL6, GADD45G, MYC, SLITRK3, JUNB, and IGFBP2) were significantly down-regulated." (PMID 33324350, 2020).
teratoma (1 paper, 2021). A non-seminomatous germ cell tumor characterized by the presence of various tissues which correspond to the different germinal layers (endoderm, mesoderm, and ectoderm). "The luciferase signal indicated that teratomas was reduced in mice transplanted with the cells expressing Gadd45g compared with mice with the cells expressing PB." (PMID 34601500, 2021).
Ureteral obstruction (1 paper, 2025). Obstruction of the flow of urine through the ureter. "GADD45γ expression is increased in rat kidneys with ureteral obstruction and renal biopsy tissue obtained from patients with chronic glomerulonephritis." (PMID 40083548, 2025).
tumor (61 papers, 2006 to 2025). "Inhibition of tumor growth in Huh-7 xenografts was associated with the induction of GADD45γ expression, increased tumor cell apoptosis (TUNEL assay), and reduced tumor angiogenesis (microvessel density)." (PMID 26172295, 2015). "Nevertheless, it is worth noting that JAK2V617F mutation is not the only regulatory mechanism responsible for the low expression of GADD45g in MPNs, and that GADD45g reduction only partially mediates the tumor-promoting activities of JAK2V617F mutation in a xenograft model of MPN." (PMID 38582902, 2024). "Indeed, expansion of the human cerebral cortex may be a result of selection for tumor growth connected with the human-specific loss of tumor suppressor gene GADD45G enhancer." (PMID 35012580, 2022). "Growth arrest and DNA damage-inducing protein 45 (Gadd45) family members, including Gadd45a, Gadd45b, and Gadd45g, have been implicated in many basic processes, such as DNA repair, genome stability, epigenetic regulation, cell cycle arrest, apoptosis, tumor development, and embryogenesis." (PMID 34601500, 2021). "Rest-repressed GADD45G is a tumor suppressor, known to be involved in the induction of apoptosis in multiple cell types, and in the neurons, it is required for memory consolidation by promoter demethylation and for neurite outgrowth." (PMID 40725218, 2025). "Downregulation of mammalian GADD45g promotes proliferation in multiple cellular contexts and tumor types." (PMID 40093151, 2025). "A deeper analysis revealed upregulation of genes involved in tumor suppression (Clca2, Spink5, Igfbp6, Nptx1, Bex4, Gadd45g, Yipf5), immune regulation (IL6ra, Ccl6, Cd81, Cd244a, Cd151, and Gata4), apoptosis, and pyroptosis (Ddit3, Rgs6, and Gsdmsc2/3/4)." (PMID 39946195, 2025). "In parallel, in vivo models such as orthotopic xenografts will be used to investigate the role of GADD45G in tumor growth, metastasis, and therapeutic response." (PMID 41018072, 2025). "Given its dual role in regulating both tumor cell invasiveness and survival, GADD45G holds promise as a potential therapeutic target and prognostic biomarker in various malignancies." (PMID 41018072, 2025). "The ectopic expression of GADD45G was shown to inhibit colony formation and tumor cell growth in silenced cell lines." (PMID 40806148, 2025). "While our cellular models revealed correlations between GADD45G expression and tumor progression as well as an EMT-like phenotype, further validation in animal models and patient-derived tissues is necessary." (PMID 41018072, 2025). "For example, tsRNA-5001a can inhibit the antitumor function of the tumor suppressor gene GADD45G by reducing its stability, which in turn enhances tumor proliferation." (PMID 40153423, 2025). "Further studies showed that tsRNA-5001a targets the growth arrest DNA damage-inducible gene 45 gamma (GADD45G), a tumor suppressor, leading to the downregulation of GADD45G." (PMID 38622694, 2024). "Overall, these findings indicate that GADD45g expression is aberrantly downregulated in MPNs, and its reduced expression acts as a tumor promoter in MPN cells." (PMID 38582902, 2024). "Ruxolitinib administration resulted in a significant reduction in tumor burden, and a prominent elevation of GADD45g expression in hCD45-positive BMMNCs, which is consistent with our in vitro observations." (PMID 38582902, 2024). "Our study revealed that genes with altered expression in tumor cells infected with the oHSV-1 virus, such as GADD45g and c-Fos, can affect the function of the virus." (PMID 39850819, 2024). "GADD45g insufficiency exerts tumor-promoting activities through the activation of RAC2-PAK1-PI3K-AKT signaling pathway." (PMID 38582902, 2024). "Evidence has shown that overexpression of GADD45G in tumor cells inhibits tumor proliferation and migration and promotes apoptosis." (PMID 36776954, 2023).
tumor (continued). "Because tumor microenvironment contributes to the malignant progression of human cancers, we performed correlation analysis between GADD45G and multiple immune cells infiltration in HCC." (PMID 37833694, 2023). "Our results describe key molecular signaling pathways, miR-301a/Gadd45g, which facilitate the direct interplay between PSCs and tumor cells." (PMID 35211358, 2022). "Decreased expression of GADD45G in esophageal cell carcinoma was correlated with tumor progression, metastasis and poor prognosis." (PMID 34299042, 2021). "GADD45γ played an important role in stress response, cell differentiation, and tumor inhibition by regulating cell proliferation and gene expression." (PMID 33080073, 2021). "The results showed that the ectopic expression of GADD45γ strongly inhibited the growth and colony formation of tumor cells in silenced cell lines." (PMID 33080073, 2021). "GADD45G has been reported to be a tumor suppressor in multiple cancer types and can inhibit cell growth and induce apoptosis." (PMID 30924596, 2019). "Here, we report that the Smad-interacting protein-1 (SIP1) is transcriptionally activated and functions critically in the GADD45G-induced tumor cell senescence." (PMID 26378039, 2015). "As expected, the mice inoculated with tumor cells with GADD45G induction (Tet+ GADD45G/Vector) developed visible tumors much later than did the mice injected with the tumor cells without inducible GADD45G expression (Control: Tet− GADD45G/Vector)." (PMID 26378039, 2015). "In the present study, we explored the biological significance of GADD45γ expression in HCC tumor tissues, and the potential predictive value of GADD45γ induction in HCC cells on the efficacy of sorafenib treatment." (PMID 26172295, 2015). "GADD45γ has been reported to be a tumor suppressor in multiple cancer types, and it can induce growth arrest and apoptosis in response to environmental stress." (PMID 26172295, 2015). "Previous studies have shown that downregulation of GADD45A and GADD45G enables tumor cells to escape programmed cell death in multiple tumor types." (PMID 26422378, 2015). "GADD45G functions as a tumor suppressive gene via activating an array of downstream effectors to induce cell growth arrest." (PMID 26378039, 2015). "Taken together, these results clearly demonstrate that SIP1 downregulation abolishes the GADD45G-mediated inhibition of tumor growth in vivo." (PMID 26378039, 2015). "Another interesting finding of our study was the increasing frequency of GADD45γ methylation with tumor progression." (PMID 25912017, 2015). "In clinical HCC specimens, GADD45G expression is inversely correlated with phosphorylated Stat3 expression in tumour cells and disease progression 91; this result was consistent with the relationship of Shp2 with Stat3 36,37." (PMID 26088100, 2015). "The expression of GADD45γ in HCC tumor tissues from patients who had undergone curative resection was measured using qRT-PCR." (PMID 26172295, 2015). "Taken together, our study demonstrates that miR-383 is a negative regulator of Gadd45g in both tumor cells and ES cells, however, has distinct function in regulating cell apoptosis." (PMID 25415264, 2014). "The mRNA expression levels of GADD45α, GADD45β, GADD45γ in tumor tissue and adjacent normal tissue from ESCC were detected." (PMID 22313682, 2012). "Until now, the GADD45 gene family, including GADD45A, GADD45B and GADD45G, has been recognized as stress sensors that modulate the response of mammalian cells to genotoxic and physiological stresses and the process of tumor formation and progression." (PMID 23110778, 2012).
tumor (continued). "It was suggested that GADD45G may function as a tumor suppressor, however frequently inactivated epigenetically in several cancer types." (PMID 40806148, 2025). "Notably, during the development of various cancer types, GADD45G is underexpressed and is regarded as a functional tumor suppressor." (PMID 41018072, 2025). "Overall, these results strongly support the role of GADD45G in inhibiting tumor metastasis." (PMID 41018072, 2025). "Additionally, cellular senescence also serves as a tumor escape mechanism; for example, GADD45G-induced senescence in hepatocellular carcinoma cells inhibits the growth of tumor cells." (PMID 40722797, 2025). "Downregulation of GADD45g plays a tumor-promoting role in human MPN cells." (PMID 38582902, 2024). "Furthermore, Dox-induced GADD45g knockdown with concurrent JAK2 inhibition led to a partial restoration of tumor burden and a shortened survival, as compared to treatment with ruxolitinib alone." (PMID 38582902, 2024). "In addition to inducing apoptosis and differentiation as well as reducing colony formation in soft agar and chemosensitivity, Gadd45g overexpression suppressed DNA repair and disease progression, suggesting a function as tumor suppressor." (PMID 37834315, 2023). "A large number of studies have shown that GADD45G is involved in the regulation of a variety of cell signaling pathways in tumor cells, and the significant reduction of their expression is closely related to tumor formation and progression." (PMID 37770840, 2023). "Notably, in the development of many different kinds of cancers, GADD45G is lowly expressed and is considered to be a functional tumor suppressor, which is similar to the result we observed in mESCs." (PMID 34601500, 2021). "Similarly, Gadd45g, as a member of the DNA damage-inducible gene family inhibiting cell growth in response to stress shock and induces apoptosis, acts as tumor suppressor gene frequently inactivated epigenetically in multiple tumors." (PMID 34872491, 2021). "The study reported that GADD45G might act as a tumor suppressor gene and upregulation inhibits cell proliferation." (PMID 34299042, 2021). "GADD45γ might be a functional tumor suppressor, which might play an important role in esophageal squamous cell carcinoma through the inactivation of proximal promoter methylation." (PMID 33080073, 2021). "Typical ones as β-defensin-1 (DEFB1), growth arrest and DNA damage-inducible gamma (GADD45G), HSP70 binding protein 21 (encoded by TTC36) that protect the organism from and down-regulated in HCC or multiple tumor types, were significantly decreased in liver of TG vs. WT pigs." (PMID 34322121, 2021). "After transplanted under the breast pads of BALB/c and nude mice, both PB and PB-Gadd45g cells could generate tumors in mice, while the tumor volumes were reduced derived from Gadd45g cells." (PMID 34601500, 2021). "Interestingly, the induced re-expression of GADD45-γ in a pituitary tumor cell line attenuated tumor cell growth by 88%." (PMID 32498309, 2020). "Although for many a function in B cells is unknown, for others (namely Arhgef1, Gadd45g, Sh2b3, and Map2k7), tumor-suppressive and/or antiproliferative activity was described." (PMID 32407433, 2020). "Gadd45g is a tumor suppressor gene that is disrupted in multiple tumor types; its down-regulation may have implications in the increased susceptibility of males to cancer." (PMID 26194646, 2016). "Therefore, comparison of GADD45γ between pre- and posttreatment tumor samples is essential to validate the concept." (PMID 26172295, 2015). "In addition, suppression of GADD45γ expression in HCC tumor tissue was observed to be an independent predictor of poor overall survival in patients with HCC who had undergone curative surgery." (PMID 26172295, 2015). "Gadd45g has been reported to be up-regulated after UV irradiation in both normal and tumor cells." (PMID 25415264, 2014).
tumor (continued). "For example, the downregulation of Onecut1 and upregulation of Ifitm3 might inhibit cell proliferation, whereas the downregulation of GADD45G might enhance tumor cell growth." (PMID 18307821, 2008). "Downregulation of GADD45G expression could enhance tumor proliferation and metastasis." (PMID 37833694, 2023). "Collectively, these data indicate that miR-301a/Gadd45g might have a general impact on PSC fate in pancreatic tumorigenesis, and provide compelling evidence that elevated Gadd45g expression contributes to attenuated tumorigenesis by modulating tumor-PSC crosstalk." (PMID 35211358, 2022). "Likewise, mRNA levels of three oncogenes, namely ETS1, MDM2, and ARAF, were decreased by C treatment; on the contrary, the growth arrest and DNA-damage-inducible G (GADD45G), a stress-responsive gene involved in tumor suppression, was upregulated in C + AFB1 exposed cells." (PMID 33137966, 2020). "Therefore, we raised the question of whether SIP1 induction is critical for GADD45G-induced tumor cell senescence." (PMID 26378039, 2015). "IRF2 also regulated GADD45G, which has been reported to enhance IFNG production and anti-tumor immune effects." (PMID 39090334, 2024). "Knockdown of PRDX1 attenuated the up-regulation of GADD45G and γ-H2AX with Celastrol or compound 19-048 treatment, which is consistent with the efficacy assessment for tumor volume and weight." (PMID 36732502, 2023). "In summary, PAX5 was found to be an epigenetically inactivated tumour suppressor that inhibits NSCLC cell proliferation and metastasis, through down‐regulating the β‐catenin pathway and up‐regulating GADD45G expression." (PMID 26843424, 2016). "We demonstrate for the first time that miR-383 can specifically regulates the expression of Gadd45g by directly targeting to the 3-UTR region of Gadd45g mRNA, a regulatory process conserved in human tumor cells and mouse embryonic stem cells." (PMID 25415264, 2014). "GADD45G and GADD45A are regulators of the cell-cycle at the G2/M transition and act as tumor suppressors." (PMID 18847459, 2008). "Only one study reported that growth arrest and DNA damage-inducible gamma (GADD45G) exerts anti-tumor effects; however, no detailed investigation has been conducted in cancers so far." (PMID 36358786, 2022). "The anti-tumour effects of Rec8 are caused by downregulation of cell growth-related genes (G6PD, SLC2A1, NOL3, MCM2, SNAI1, and SNAI2) and also by upregulation of both apoptosis or migration inhibitors (Gadd45G and LDHA) and tumour inhibitors (PinX1, IGFBP3, and ETS2)." (PMID 36139540, 2022). "Upregulation of Gadd45g impaired homologous recombination DNA repair and dramatically induced tumor cell apoptosis without affecting normal cells." (PMID 35211358, 2022). "There were many studies on the relationship between GADD45γ and tumor in solid tumors and AML; however, up to now, there is no report in MDS." (PMID 33080073, 2021). "GADD45γ mRNA was more suppressed in HCC tumor tissue than in the adjacent nontumor liver tissue, and the median T to non-T ratio of GADD45γ mRNA was 33.8% (0.7%–974.0%)." (PMID 26172295, 2015). "The hazard ratio of death was 2.94 (95% CI 1.27–6.77, p = 0.012) for patients with low GADD45γ expression (tumor to nontumor ratio of < 33.8%)." (PMID 26172295, 2015). "GADD45γ overexpression in Huh-7R xenografts, achieved using adenoviral transfer, did not demonstrate tumor-suppressing effects by itself." (PMID 26172295, 2015).
tumor (continued). "Tumor cell lines previously lacking GADD45-γ expression that were transfected with GADD45-γ showed significant reduction in colony formation and some cases with frank apoptosis and no culture growth." (PMID 17026765, 2006). "The decrease or absence of GADD45γ expression might be the reason why tumor cells or precancerous hepatocytes bypass cell aging." (PMID 33080073, 2021). "Based on the fact that GADD45γ could inhibit tumor growth by promoting apoptosis, and it had been reported that GADD45γ has biological activity in AML treatment, this study first analyzed the expression level of GADD45γ in MDS patients' bone marrow cells." (PMID 33080073, 2021). "However, using GADD45-γ in liquid biopsies will not allow for localization of the tumor as it is already exploited in the treatment of other types of cancer." (PMID 32498309, 2020). "Moreover, the immunostaining results showed that, in the presence of GADD45G induction, the expression of the proliferation marker Ki-67 was robustly augmented in the tumor cells with SIP1 inhibition relative to those without SIP1 shRNA expression." (PMID 26378039, 2015). "Expression of GADD45B or GADD45G was not significantly different between the tumor groups." (PMID 17280610, 2007). "However, the average latency for tumor onset in the group with shRNA-mediated SIP1 inhibition and GADD45G induction (Tet+ GADD45G/shSIP1), was comparable to that in the groups without GADD45G expression, and much shorter than that in the group with GADD45G induction alone (Tet+ GADD45G/Vector )." (PMID 26378039, 2015).